CD1C (CD1c molecule)
Description:
Antigen-presenting protein that binds self and non-self lipid and glycolipid antigens and presents them to T-cell receptors on natural killer T-cells.
Synonyms: BDCA1; CD1; R7
Tractability: Small molecule: a structure with a bound ligand is known. Antibody: UniProt places it where antibodies can reach, with high confidence; its Gene Ontology location is reachable by antibodies, with high confidence; UniProt predicts a signal peptide or a membrane-spanning region. PROTAC: ubiquitination databases record sites on it.
Gene: Protein-coding gene on chromosome 1 (158,289,923 to 158,294,774, forward strand). Ensembl gene ENSG00000158481.
Subcellular location: Cell membrane; Endosome membrane; Lysosome
Subcellular location (Human Protein Atlas): Golgi apparatus; Vesicles; Endoplasmic reticulum
Pathways (Reactome):
Immune System: Immunoregulatory interactions between a Lymphoid and a non-Lymphoid cell
Gene Ontology:
Molecular function: endogenous lipid antigen binding; exogenous lipid antigen binding; glycolipid binding; lipopeptide binding; protein binding
Biological process: T cell activation involved in immune response; antigen processing and presentation, endogenous lipid antigen via MHC class Ib; antigen processing and presentation, exogenous lipid antigen via MHC class Ib; immune response; positive regulation of T cell mediated cytotoxicity
Cellular component: endosome membrane; lysosome; plasma membrane; external side of plasma membrane
Genetic constraint (gnomAD): Loss-of-function variants: 47 observed, 42.43 expected, observed/expected ratio (o/e) 1.11, 90% interval 0.88 to 1.41. The upper end of that interval is the gene's LOEUF score, 1.41, which puts it in group 5 of 6, group 1 being the genes least tolerant of losing a copy. Missense variants: 417 observed, 414.82 expected, observed/expected ratio (o/e) 1.01, 90% interval 0.93 to 1.09. Synonymous variants: 165 observed, 159.04 expected, observed/expected ratio (o/e) 1.04, 90% interval 0.91 to 1.18.
Homologues: Orthologues: chimpanzee CD1C (98% identical), macaque CD1C (91% identical), guinea pig Cd1c3 (66% identical), guinea pig Cd1c1 (65% identical), dog CD1B (63% identical), guinea pig Cd1c2 (60% identical), zebrafish mhc1laa (21% identical), zebrafish mhc1lfa (20% identical), zebrafish mhc1lja (20% identical), zebrafish mhc1lda (19% identical), zebrafish mhc1lla (19% identical), zebrafish si:dkey-52p2.5 (19% identical), and 3 more. Paralogues in human: CD1B (60% identical), CD1A (57% identical), CD1E (52% identical), CD1D (50% identical), HLA-F (23% identical), HLA-A (23% identical), HLA-E (23% identical), HLA-G (23% identical), HLA-C (22% identical), HLA-B (22% identical), MR1 (20% identical), HFE (20% identical), and 10 more.
Diseases named in the same sentence as CD1C in open-access papers:
CD1C is named in the same sentence as 160 diseases in open-access papers, as found by Europe PMC text mining. Sharing a sentence is not in itself a finding about the gene and the disease. The quoted sentences say what the papers report.
melanoma (29 papers, 2016 to 2025). A malignant, usually aggressive tumor composed of atypical, neoplastic melanocytes. "Specifically, the use of autologous CD1c+ DCs has been linked to long-term progression-free survival (12–35 months) in a subset of melanoma patients." (PMID 39062753, 2024). "The presence of tumor-associated CD1c+CD14+ DCs has been reported in multiple studies including melanoma, breast cancer, ovarian cancer, and head and neck cancer." (PMID 38242119, 2024). "In melanoma, vaccination with pDCs or CD1c+ DCs caused secretion of different chemokines and recruitment of different immune effector cells, in particular, pDCs induced a stronger influx of cytolytic lymphocytes than CD1c+ DCs." (PMID 35311157, 2022). "For stage III and IV melanoma patients receiving CD1c+ DC-based vaccinations, the presence of CD1c+CD14+ DCs (DC3) in vaccine preparations suppresses CD4+ T cells." (PMID 40789452, 2025). "The enrichment of CD1c+CD14+ cells with low immunostimulatory capability in melanoma and NSCLC prompted us to study their development." (PMID 38242119, 2024). "Melanoma patient-derived CD1c+ DC vaccine preparations containing a larger fraction of CD14+ cells significantly hampered T cell activation." (PMID 38242119, 2024). "In NSCLC and melanoma patients, the majority of CD1c+ cells, on average 59% and 68%, respectively, expresses CD14." (PMID 38242119, 2024). "Clinical trials in prostate cancer and melanoma have not only confirmed the safety and feasibility of using blood-derived cDC2s CD1c+ with TAA peptides but also suggested an improvement in progression-free survival rates." (PMID 39062753, 2024). "In the peripheral blood of stage III and IV melanoma patients, CD1c+CD14+ frequencies were increased compared with healthy individuals." (PMID 38242119, 2024). "In melanoma patients undergoing CD1c+ DC vaccinations, increased CD1c+CD14+ DC frequencies correlate with reduced survival." (PMID 38242119, 2024). "In contrast, CD14+ CD1c+ DC have been shown in blood of healthy controls and melanoma patients, albeit showing immune-inhibitory functions." (PMID 36685500, 2022). "Similar to our findings, CD14+CD1c+ found in melanoma patients showed a higher degree of uptake compared to CD1c+ DCs." (PMID 34359719, 2021). "Tumor-infiltrating CD14+CD1c+ DCs have been reported in multiple instances, including ovarian cancer ascites, breast cancer, and melanoma." (PMID 32610077, 2020). "Together, these findings were taken to design an optimized cellular vaccine, in which the CD14+ subset is removed from the CD1c+ DC product for vaccination of patients with melanoma and other malignancies." (PMID 33101275, 2020). "This is in line with our previous study in stage IV melanoma patients vaccinated with CD1c+ DCs (cDC2), in whom the presence of functional tumor antigen-specific T cells in SKIL cultures coincided with improved clinical outcome." (PMID 31727154, 2019). "Previously, we studied the safety, immunogenicity and clinical efficacy of pDC and CD1c+ mDC vaccinations in stage IV melanoma patients." (PMID 31727154, 2019). "PBMC cultures in the presence of melanoma cells also showed an increased percentage of CD1c+ DCs (CD33+CD14−HLA-DR+CD1c+) among leukocytes, with a trend toward melphalan-exposed melanoma cells inducing the highest expansion of DCs." (PMID 30560089, 2018). "Another DC population characterized by CD1c+CD14+CD16− expression was found in the blood of melanoma patients and exhibited immunosuppressive functions by suppressing T-cell proliferation in an antigen-specific manner." (PMID 29250057, 2017). "Naïve and memory CD4+ T-cell stimulation.Th17 polarization.DC-10, skin CD141+CD14+ DCs and CD1c+CD14+ DCs in melanoma patients promote tolerance." (PMID 29250057, 2017).
melanoma (continued). "Though large clinical trials are needed to define which DC subsets provide optimal therapeutic efficacy in particular settings, early trials with plasmacytoid DC (pDC) and CD1c+ myeloid DC (mDC) have both shown promise in melanoma patients." (PMID 29209327, 2017). "In our cohort of melanocytic lesion samples, we found a statistically significant increase in the number of CD1c-positive cells in the epidermis of melanoma in situ and invasive tumors when compared with dysplastic nevi." (PMID 28331853, 2017). "CD1c+ myeloid DCs and plasmacytoid DCs (pDCs) have been successfully utilized in clinical vaccination trials against melanoma." (PMID 27853652, 2016). "Our group has previously conducted phase I clinical trials exploiting either pDCs or CD1c+ DCs for vaccination of melanoma patients, demonstrating the safety and efficacy of this approach." (PMID 27853652, 2016). "Similarly, lower numbers of epidermal CD1c+ DCs were found in invasive and in situ melanoma tissues in comparison with dysplastic nevi." (PMID 35955602, 2022). "In melanoma patients, the frequency of the CD1c+CD14+ cells increased, and for the DC vaccination strategy used in these patients, CD1c+CD14+ cells were omitted from the optimized protocol and might be even a potential target to improve immunotherapy." (PMID 34359719, 2021). "Furthermore, the CD1c+ CD14+ inf-DC-like populations that accumulate in melanoma nodules are hypostimulatory for allogenic T cells and have high cell surface expression of PD-L1." (PMID 30979057, 2019). "A population of CD1c+ CD14+ DC that may be related to inf-DC have been detected in skin lesions of melanoma patients." (PMID 30979057, 2019). "Likewise, immunization of stage IIIc/IV melanoma patients with autologous, peptide-pulsed CD1c+ mDC promoted Ag-specific CD8+ T cell responses in 33% of tested patients and induced long-term progression-free survival (12–35 months) in nearly 30% of patients." (PMID 29209327, 2017). "Analysis of correlation between CD1c+CD14+ frequencies and progression-free survival (PFS) for responding melanoma patients showed that high CD1c+CD14+ frequencies in the vaccine correlate with shorter PFS (R2 = 0.9570, p = 0.0038, n = 5)." (PMID 38242119, 2024). "identify tumor-induced CD1c+CD14+ DC3s, increased in melanoma and NSCLC patients, originating from DC2s upon exposure to tumor-derived IL-6 and M-CSF." (PMID 38242119, 2024). "We first determined the balance between CD1c+CD14− cells and CD1c+CD14+ cells in peripheral blood of early-stage NSCLC and stage III and IV melanoma patients by flow cytometry and compared this with healthy donors (HDs)." (PMID 38242119, 2024). "To answer these questions, we set out to characterize CD1c+CD14+ cells in NSCLC and investigate their development in the context of melanoma and NSCLC." (PMID 38242119, 2024). "CD1c+CD14+ cells are detected in a variety of cancers, such as ovarian, breast cancer, and melanoma." (PMID 34359719, 2021). "In previous studies, we established that TAMs are the most abundant type of myeloid cells in melanoma tissues, as compared with other mononuclear (CCR2+ monocytes or CD1c+ myeloid DCs) and polymorphonuclear phagocytes." (PMID 34439098, 2021). "In blood of melanoma patients with metastatic disease, the frequency of the CD14+ subset of CD1c+ cells in blood was found to be increased more than three-fold." (PMID 33101275, 2020). "Finally, based on the observed systemic effect of tumors on CD1c+CD14+ cell frequencies in patients, we cultured CD14− cDC2s with melanoma patient or HD serum." (PMID 38242119, 2024). "In a phase I study, the usage of IT injection of T-VEC and CD1c (BDCA-1)+ myeloid dendritic cells (myDCs) as well as CD141 (BDCA-3)+ myDCs in advanced melanoma patients who did not respond to standard therapy was evaluated (NCT03747744)." (PMID 39065766, 2024).
melanoma (continued). "Melanoma, testicular cancer or colorectal cancer cells that were exposed to cisplatin or oxaliplatin could enhance the phagocytosis of CD16+ DCs, CD1c+ DCs, and pDCs and encourage them to gain a mature phenotype." (PMID 32655564, 2020). "CD1c+ mDCs are highly efficient antigen-presenting cells that have the ability to secrete IL-12p70, while pDCs are professional IFN-α-secreting cells that are shown to induce innate immune responses in melanoma patients." (PMID 30019146, 2018). "Our finding indicates that epidermal area of melanomas might not be adequately equipped with CD1c-positive DC subset and thereby might be unable to elicit an appropriate antitumor immune response." (PMID 28331853, 2017). "Utilizing melanoma and NSCLC cell lines we show that CD1c+CD14+ cells emerge from cDC2s but not monocytes, through IL-6 and macrophage colony-stimulating factor (M-CSF/CSF1) secreted by tumor cells." (PMID 38242119, 2024). "In a study assessing melanoma and NSCLC, both tumors with high immune infiltration, researchers found that non-mature CD1c+ CD14- cDC2s could be directed towards DC3s (CD1c+ CD14+ cDC2s) through tumor-derived IL-6 and M-CSF (CSF1)." (PMID 40584260, 2025). "DC markers HLA-DR, CD86, CD1c, ILT3 and CD40 did not significantly differ among the outcome groups in mitochondrial populations, however their expression was significantly elevated in the melanoma bad and good outcome groups as compared to HD in the glycolytic cell states." (PMID 37938561, 2023).
COVID-19 (18 papers, 2021 to 2025). A disease caused by infection with severe acute respiratory syndrome coronavirus 2. "Considering the majority myeloid populations in NALT, ‘IFNα response’ and ‘INFγ response’ genes were significantly enriched in macrophages, CD1C+ dendritic cells (DCs) and pDCs in acute COVID-19 compared with controls." (PMID 39890933, 2025). "Interleukin (IL)-6 concentrations were significantly increased in COVID-19 patients (p < 0.0001 vs. controls), and negatively correlated with the absolute counts of circulating CD1c+ cDC2 (r = −0.29, p = 0.034) and CD303+ pDC (r = −0.29, p = 0.036) subsets." (PMID 38731010, 2024). "Through the application of Mendelian randomization methodology, two immune genes, CD1C and IL1B, have been identified as exhibiting the closest association with COVID-19." (PMID 39622956, 2024). "CD1C’s role in dendritic cell function suggests its importance in modulating the immune response during COVID-19." (PMID 39622956, 2024). "In severe COVID-19, dendritic cells (DCs) and a specific subset, CD1c+ conventional dendritic cells (cDCs), significantly decreased, implying a link with poor prognosis." (PMID 35335635, 2022). "A decrease in peripheral blood CD1c+ mDC numbers has been found in patients with severe COVID-19, due to a migration of these cells from blood to the lungs." (PMID 35943812, 2022). "Severe COVID-19 patients contained lower proportions of CD1c+ mDC compared to mild patients, and lower proportions of pDC and CD1c+ mDC compared to healthy donors." (PMID 33692788, 2021). "This study found a more pronounced reduction in CD1C levels among patients with severe COVID-19." (PMID 39622956, 2024). "Correlation analysis between IL-6 serum levels and the distribution of all DC subtypes further showed that in COVID-19 patients, IL-6 was negatively relatedto the circulating absolute levels of the CD1c+ cDC2 subpopulation (r = −0.29, p = 0.034) and CD303+ pDC subsets (r = −0.29, p = 0.036)." (PMID 38731010, 2024). "Furthermore, the proportion of CD1C+ DCs was markedly higher in healthy controls compared to COVID-19 patients, suggesting a positive correlation between elevation of mregDCs and the progression of SARS-CoV-2 infection-induced sepsis." (PMID 35832091, 2022). "Consistent with the progressive changes in abundance according to COVID-19 severity, the frequencies of cycling cMono and S100A8/9/12hiHMGB2 expressing cMono, and CD1c+ cDCs, were associated with clinical variables relating to oxygenation and respiratory function in hospitalized cases." (PMID 35216673, 2022). "pDCs showed reduced abundance in more severe COVID-19, influenza, and sepsis, as did CD1c+ cDCs." (PMID 35216673, 2022). "The presence of CD1C (IVW OR = 0.804, 95% CI: 0.658 − 0.984, p = 0.034), IL1B (IVW OR = 0.846; 95% CI: 0.732–0.978; p = 0.024), and SLPI (IVW OR = 0.862; 95% CI: 0.751–0.990; p = 0.035) may be associated with a lower risk of COVID-19." (PMID 39622956, 2024). "Therefore, it is possible that the lower frequency of CD1c+ in severe COVID-19 patients might be related to their increased migration to the lungs, reduced HLA-DR expression, and activation." (PMID 33692788, 2021). "In this study, we further explored the relationship between CD1C and IL1B genes discovered in the COVID-19 GWAS dataset and immune infiltration." (PMID 39622956, 2024). "The significant downregulation of CD1C and IL1B in the COVID-19 patient group, consistent with the MR analysis results, underscores their potential role as protective genes." (PMID 39622956, 2024). "Among these genes, CD1C, IL1B, and SLP1 have emerged as key IRGs with potential protective effects against COVID-19." (PMID 39622956, 2024). "According to previous studies, Langerhans cell histiocytosis (LCH), COVID-19, and systemic lupus erythematosus (SLE) are related to the level of CD1C+ DC cells." (PMID 36755259, 2023).
COVID-19 (continued). "Overall, these findings underscore the potential of CD1C and IL1B as biomarkers for predicting the onset and progression of COVID-19, which could inform therapeutic strategies." (PMID 39622956, 2024). "Research also indicates that Th17 differentiation is closely related to COVID-19 75, so it can be inferred that CD1C and IL1B may influence the occurrence and development of COVID-19 through the Th17 differentiation pathway." (PMID 39622956, 2024). "In contrast, the expression of FCER1A, HLA-DMB, and CD1C was not different between severe COVID-19 and non-COVID-19 patients." (PMID 38262689, 2024). "Focusing on DCs, we found a significant relative reduction of cDC1 (CD123– CD141+ CD1clo), cDC2 (CD123– CD141lo CD1c+ CD5+), DC3 (CD123– CD141lo CD1c+/int CD5–) and pDC (CD123+ Axl−Siglec1–) within the Lin−HLA-DR+ CD88/89– CD16– population in COVID-19 patients compared to controls." (PMID 34614036, 2021). "etc.)and genes (CD1C, IL1B) that may play important roles in COVID-19." (PMID 39622956, 2024). "In addition, GSEA analysis identified a negative relationship between KLRB1 and CD1C expression and the severe phenotype of COVID-19 patients." (PMID 38262689, 2024). "Importantly, while inflammatory monocytes and CD1c+ conventional DC were present in lung infiltrates of patients with severe COVID-19, CD123hi pDC were depleted in blood but absent in the lungs." (PMID 34473805, 2021).
rheumatoid arthritis (18 papers, 2013 to 2025). A chronic, systemic autoimmune disorder characterized by inflammation in the synovial membranes and articular surfaces. "To date, rheumatoid arthritis (RA) researchers have predominantly focused on a potential pathogenic role for CD1c+ DCs." (PMID 29867920, 2018). "Here the authors show that miR-34a targets Axl to control CD1c+ DC activity in mice, and that miR-34a-deficient mice are resistant to collagen-induced arthritis, whereas DCs from patients with rheumatoid arthritis have high levels of miR- 34a." (PMID 28639625, 2017). "Furthermore, we identify several associations of autoimmune diseases with proteins in the immune pathway including inflammatory bowel disease with T-cell surface glycoprotein (CD1C) and rheumatoid arthritis with B-cell antigen receptor complex-associated protein beta chain (CD79B)." (PMID 37550624, 2023). "In rheumatoid arthritis, synovial fluid contains increased numbers of activated CD1c+ dendritic cells that stimulate CD4+ T cells, although CD1c restriction was not definitively proven." (PMID 40709176, 2025). "A population of synovial inflammatory DCs (CD14+ infDCs; CD1c+CD14+CD16−) has been identified in inflamed SF samples of patients with rheumatoid arthritis (RA)." (PMID 32849606, 2020). "The aim of this study was to investigate PD-1/PD-L1 involvement in the hyporesponsiveness of rheumatoid arthritis (RA) synovial fluid (SF) CD4 T cells upon stimulation by thymic stromal lymphopoietin (TSLP)–primed CD1c myeloid dendritic cells (mDCs)." (PMID 25433812, 2014). "Further mechanistic hypotheses enabled by the integration of our HLA-pQTL with HLA-disease data are the effect of HLA-B position 114 DK on the CD1C gene and rheumatoid arthritis." (PMID 39085222, 2024). "The individual contribution of specific myeloid subsets such as CD1c+ conventional DC (cDC) to perpetuation of rheumatoid arthritis (RA) pathology remains unclear." (PMID 36194479, 2022). "CD1c on B cells is responsible for presenting lipid antigens to T cells, including self-antigens, and the responding self-reactive T cells contribute to autoimmune diseases such as rheumatoid arthritis." (PMID 28617321, 2017). "The number of CD1c+DCs in SLE patients was markedly decreased compared to healthy controls (HC) and patients with rheumatoid arthritis (RA)." (PMID 31175312, 2019).